TIMM10 (translocase of inner mitochondrial membrane 10)
Description:
Mitochondrial intermembrane chaperone that participates in the import and insertion of multi-pass transmembrane proteins into the mitochondrial inner membrane. May also be required for the transfer of beta-barrel precursors from the TOM complex to the sorting and assembly machinery (SAM complex) of the outer membrane. Acts as a chaperone-like protein that protects the hydrophobic precursors from aggregation and guide them through the mitochondrial intermembrane space.
Synonyms: TIM10; TIM10A; TIMM10A
Tractability: Small molecule: a structure with a bound ligand is known. Antibody: UniProt places it where antibodies can reach, with high confidence. PROTAC: ubiquitination databases record sites on it; its protein half-life has been measured.
Gene: Protein-coding gene on chromosome 11 (57,528,406 to 57,531,031, reverse strand). Ensembl gene ENSG00000134809.
Subcellular location: Mitochondrion inner membrane
Subcellular location (Human Protein Atlas): Mitochondria
Pathways (Reactome):
Metabolism of proteins: Mitochondrial protein degradation
Protein localization: Mitochondrial protein import
Gene Ontology:
Molecular function: protein binding; protein homodimerization activity; protein-folding chaperone binding; membrane insertase activity; zinc ion binding
Biological process: protein insertion into mitochondrial inner membrane; establishment of protein localization to membrane
Cellular component: mitochondrial inner membrane; mitochondrial intermembrane space; mitochondrial intermembrane space chaperone complex; mitochondrion; TIM22 mitochondrial import inner membrane insertion complex; TIM23 mitochondrial import inner membrane translocase complex
Genetic constraint (gnomAD): Loss-of-function variants: 13 observed, 9.65 expected, observed/expected ratio (o/e) 1.35, 90% interval 0.86 to 1.88. That is too few expected variants to judge how well the gene tolerates losing a copy. Missense variants: 82 observed, 119.59 expected, observed/expected ratio (o/e) 0.69, 90% interval 0.57 to 0.82. Synonymous variants: 40 observed, 44.83 expected, observed/expected ratio (o/e) 0.89, 90% interval 0.69 to 1.16.
Homologues: Orthologues: chimpanzee TIMM10 (100% identical), macaque TIMM10 (100% identical), mouse Timm10 (100% identical), pig TIMM10 (100% identical), rabbit TIMM10 (100% identical), rat Timm10 (100% identical), dog TIMM10 (99% identical), guinea pig TIMM10 (99% identical), tropical clawed frog timm10 (89% identical), zebrafish timm10 (79% identical), Drosophila melanogaster Tim10 (60% identical), Caenorhabditis elegans tin-10 (52% identical).
Diseases named in the same sentence as TIMM10 in open-access papers:
TIMM10 is named in the same sentence as 8 diseases in open-access papers, as found by Europe PMC text mining. Sharing a sentence is not in itself a finding about the gene and the disease. The quoted sentences say what the papers report.
asthma (1 paper, 2023). "However, the role of TIMM10 and NDUFAB1 in asthma requires further investigation." (PMID 37152983, 2023).
breast carcinoma (1 paper, 2011). "Likewise, we confirmed the up-regulation of seven genes (BID, MRRL17, SH3PB5, MRRL49, TK1, TIMM10, and UNG) in rho0 cells and breast cancer cell lines." (PMID 21935467, 2011).
COVID-19 (1 paper, 2025). A disease caused by infection with severe acute respiratory syndrome coronavirus 2. "In influenza, UBE2S, USP53, and TIMM10 were observed in this category, while in COVID-19, UBE2T, UBE2C, DTL, MT-ND2, UCHL1, and UBA52 were implicated." (PMID 41020849, 2025).
viral infection (1 paper, 2021). "The top genes in the individual LIMMA analyses that were differentially expressed in peripheral blood samples of patients hospitalized with viral infection vs. bacterial (baseline in the model) infection were ISG15, TIMM10, IFI27, IFI44L and OAS2." (PMID 34593881, 2021).
tumor (1 paper, 2023). "The gene expression profiles suggested that the expression levels of CDC20, UQCRH, TIMM10, TIMM13, POLR2L, and NDUFAB1 were upregulated in tumor tissue." (PMID 36901944, 2023).
TIMM10 also shares sentences with these, for which no sentence is quoted: infection (1 paper); influenza (1); lung carcinoma (1).